ALB (albumin)
Diseases named in the same sentence as ALB in open-access papers (continued):
Sharing a sentence is not in itself a finding about the gene and the disease.
diabetes (continued). "Moreover, the CKD patients with diabetes had lower serum albumin and a higher proportion of hypomagnesemia and osteoporosis." (PMID 26273297, 2015). "For example, albumin (major circulating protein) undergoes increased glycoxidation with diabetes and may represent an important biomarker for monitoring diabetic pathophysiology." (PMID 25878764, 2015). "Novel data are included showing how AGEs (especially glycated albumin) may be involved in hyperglycemia-induced oxidative damage in adipocytes and its potential links to diabetes progression." (PMID 25878764, 2015). "In vivo, the proportion of glycated albumin in healthy persons is between 1% and 10%; this proportion may increase two- to threefold in diabetes mellitus." (PMID 24747646, 2014). "We speculated that subjects diagnosed with diabetes were more inclined to receive further treatment, which may correct their urinary albumin excretion." (PMID 25500578, 2014). "Similar associations were observed in patients with and without diabetes except for pre-albumin, which was related to low urinary creatinine excretion only in those with diabetes." (PMID 25401694, 2014). "Moreover, the male gender, age, diabetes, albumin, hemoglobin, t-bilirubin, iron, TIBC, potassium, phosphate, and uric acid showed a significant relation with serum TC levels." (PMID 25489602, 2014). "The proportion of diabetes and β-blocker, serum blood urea nitrogen, phosphate and high-sensitivity C-reactive protein levels, and urine protein-creatinine ratio increased and eGFR, serum hemoglobin, calcium, and albumin levels decreased with Ang-2 quartiles." (PMID 25279852, 2014). "Fourteen candidate predictors (age, sex, BMI, smoking status, systolic blood pressure, macrovascular complications, insulin dependency, duration of diabetes, retinopathy, treatment modality, Karnofsky scale, hemoglobin level, serum phosphate and serum albumin) were included in this analysis." (PMID 24594735, 2014). "Diabetes mellitus, older age, peripheral artery disease, stroke history, female gender, and African-American race were associated with worse SPPB scores, and higher serum albumin concentration was associated with higher scores." (PMID 25399253, 2014). "For instance, carbohydrates could bind to albumin via three main sites (Lys-351, Lys-475 and Arg-117), and as so, albumin may protect other proteins from glycation in the initial stages of diabetes." (PMID 24708663, 2014). "We used the Evans blue-albumin method to detect diabetes-induced retinal vascular leakage." (PMID 25356875, 2014). "Glycated albumin, because of its shorter half-life (21 days) compared with hemoglobin, could be used as a shorter-term glycemic control for diabetes." (PMID 24708663, 2014). "However, FBG and TG levels were significantly higher in all diabetes groups than the NC group, and serum albumin concentration was significantly lower in diabetes groups than the NC group." (PMID 24936866, 2014). "Since glycation of albumin impairs the antioxidant activities of albumin, GA may contribute to increased oxidative stress in patients with diabetes." (PMID 25314300, 2014). "Based on multivariate regression analysis that included albumin (≥4.0 g/dl), γ-GTP (≥44 IU/L), leptin (≥8.6 ng/ml), resistin (≥8.8 ng/ml), hyaluronic acid (≥76.4 ng/ml), presence of diabetes, and age (≥55 years), leptin was independently associated with hepatic steatosis." (PMID 24524410, 2014). "We further investigated the effects of other urinary components, commonly encountered in clinical settings, such as albumin and creatinine (kidney diseases), glucose (diabetes), calcium (urinary stones), gentamicin and tobramycin (antibiotics for urinary tract infection)." (PMID 25275511, 2014).
diabetes (continued). "Out of nine tested parameters (age, duration of diabetes, systolic and diastolic blood pressure, albumin excretion rate, serum HbA1c, CRP, TGF-β1, and creatinine), it turned out that TGF-β1 in serum had the most discriminative power in predicting the occurrence of DR in juvenile patients with T1DM." (PMID 23671881, 2013). "SBP, serum albumin, CRP were significantly associated with microalbuminuria (p value for uric acid was 0.068) while additional risk factors including total cholesterol, ALT, cystatin C and diabetes were significantly associated with overt albuminuria." (PMID 23947772, 2013). "Univariate analyses revealed that mean CCA-IMT was positively correlated with age, systolic blood pressure, brachial-ankle pulse wave velocity (PWV), urinary albumin excretion and duration of diabetes, but was negatively correlated with diastolic blood pressure and fasting plasma glucose." (PMID 24373412, 2013). "Previous reports of GH antagonist treatment from the onset of diabetes found a normalization of diabetes-induced renal effects, including reduced renal hypertrophy, glomerular hypertrophy, and urine albumin content; however, these studies were only in male experimental animals." (PMID 23805912, 2013). "In fact, many researchers believe that non-enzymatic glycation of albumin can alter its structure and function e.g., its binding properties, which in turn can leave many deleterious impacts in association with diabetes mellitus-related metabolic disorders." (PMID 24250587, 2013). "Although these clinical parameters may influence the mortality rate, the CCI still performed better than age, diabetes, cardiovascular disease, or albumin." (PMID 24040407, 2013). "The most common goals set by participants in the worksheet for their patients with diabetes were for achievement of target BP (i.e., increase the proportion of patients meeting BP target, three times) and increasing testing rates of urinary albumin-to-creatinine ratio (three times)." (PMID 24341511, 2013). "Diabetes, elevated SBP and lower serum albumin were independently associated with higher hs-TnT." (PMID 24148285, 2013). "We report that lowering plasma AGA by administration of 23CPPA reduces the elevated urinary excretion of these analytes as well as of albumin, which is increased in the streptozotocin diabetic rat, but not the hyperfiltration that is observed in this experimental animal model of diabetes." (PMID 24303153, 2013). "However, MyD88-dependent pathways were less clearly involved in diabetes-induced alterations in albumin accumulation in the retina or leukocyte-mediated killing of endothelial cells." (PMID 23874797, 2013). "Longitudinal studies of CKD patients have identified both modifiable and non-modifiable risk factors of CKD progression, including age, sex, race, hypertension, urinary albumin excretion (UAE), diabetes, low HDL-cholesterol, and the underlying cause of nephropathy." (PMID 24349134, 2013). "Finally, BMD of total spine (L1–L4) and hip was positively correlated with BMI and negatively correlated with age, duration of diabetes, and 24 h urinary albumin." (PMID 23401682, 2013). "Diabetic mice treated with a specific GH receptor antagonist showed none of the diabetes-associated renal hypertrophy or glomerular enlargement and had lower urinary albumin excretion than untreated diabetic mice." (PMID 23805912, 2013). "Improve patterns of diabetes care as measured by whether the frequency of testing for hemoglobin A1c, blood lipids and urinary albumin meets NHMRC (National Health and Medical Research Council) guidelines." (PMID 23497486, 2013). "In addition, many cross-sectional and prospective studies have been carried out in Caucasian populations, which have identified several risk factors of DR, including duration of diabetes, SBP, glycemic control, and urinary albumin." (PMID 22844279, 2012).
diabetes (continued). "The high incidence of infections might be due to diabetes, low albumin, elevated intracellular calcium, acidosis, or repetitive vascular procedures." (PMID 22830039, 2012). "From a clinical perspective, the value of glycated albumin determination has been further highlighted by reports of the strong correlation between glycated albumin concentrations and the development of serious diabetes complications including nephropathy, retinopathy and arterial stiffening." (PMID 22393405, 2012). "Risk factors include high serum phosphate level with increased calcium phosphate product, secondary hyperparathyroidism, and use of calcium containing phosphate binders, use of calcitriol, diabetes mellitus, obesity, low albumin, Coumadin therapy, female gender, and Caucasian race." (PMID 24533203, 2012). "Second, we were unable to identify CKD with causes other than diabetes and did not have complete data with respect to urine albumin testing." (PMID 22776036, 2012). "There also exists evidence that when podocytes in cell cultures are treated with angiotensin and glycated albumin (insults relevant to diabetes), there is shedding of extracellular domain of the nephrin molecule from podocyte cell surface into the urinary space." (PMID 22615747, 2012). "Glycation of glucose to human serum albumin in vivo is related to diabetes and many other diseases." (PMID 22832880, 2012). "Early renal dysfunction may be predicted by the early rise in NAG in diabetes as the majority of patients may also show glomerular hyperfiltration and increased urinary albumin excretion." (PMID 22966455, 2012). "GFR < 45 ml/min/1.73 m2, age ≥ 61 years, CVD, diabetes, CRP ≥ 5 mg/L, Hb ≤ 110 g/L, p-albumin ≤ 35 g/L and overweight were all associated to impaired HRQoL, indicating that HRQoL related to renal function level, as well as to other conditions associated to CKD, like inflammation and CVD." (PMID 22710013, 2012). "The addition of five markers, including the BMI, presence of diabetes/impaired fasting glucose, AAR, platelet count, and albumin concentration, to the ELF test improved its diagnostic accuracy, with AUROCs of 0.98, 0.93, and 0.84 for the diagnosis of severe, moderate and no fibrosis, respectively." (PMID 22110476, 2012). "Furthermore, it is widely accepted that microalbuminuria (albumin urinary excretion of 30 mg–300 mg/day) is the earliest clue about the renal involvement of diabetes, obesity, and the metabolic syndrome." (PMID 22844592, 2012). "Dysfunction of albumin reabsorption in the proximal tubules, due to reduced megalin expression, may explain the microalbuminuria in early-stage diabetes." (PMID 22685655, 2012). "Using linear regression model, taking Ci as continuous dependent variable, chemerin concentration was independently correlated to Ci (standardized β = 0.26, P<0.001) after adjusted for fetuin A levels, age, gender, diabetes mellitus status, HD vintage, albumin and Kt/Vurea." (PMID 22815691, 2012). "Hemoglobin concentration was positively correlated with body mass index, HbA1c, estimated glomerular filtration rate, cholinesterase, and 25-hydroxyvitamin D level and negatively correlated with age, duration of diabetes mellitus, serum creatinine, and urinary albumin creatinine ratio." (PMID 21754928, 2011). "Hazards ratios are adjusted for age, sex, previous CVD events, diabetes mellitus and time-dependent type of renal replacement therapy (Model 1) and an extended adjustment additionally for albumin, CRP, current smoking, native fistula and ejection fraction (Model 2 as sensitivity analysis)." (PMID 21408188, 2011). "Likewise, all three doses of the drug also seemed to inhibit any diabetes-induced increase in albumin accumulation in the neural retina." (PMID 22171162, 2011).
diabetes (continued). "In this multivariable linear regression analysis adjusted for country effects, older age, male gender, lower serum albumin, lower BMI, diabetes, higher systolic blood pressure, and use of at least once per day highest hypertonic glucose were associated with higher relative tissue hydration." (PMID 21390320, 2011). "In the present investigation, we also found plasma vitamin C positively related with albumin in Spearman correlation analysis, but the association did not exist after adjustment for sex, age, diabetes, mode of dialysis and other confounding effects." (PMID 21548917, 2011). "In patients with congestive heart failure but without diabetes or hypertension, increased urinary albumin predicts both CV and all cause mortality independent of reduced GFR." (PMID 25013588, 2011). "Analysis of each of these variables by age showed a significant age trend for BMI, waist-hip ratio (marker of central adiposity), alcohol use, systolic blood pressure, elevated cholesterol, prevalence of diabetes, leptin, adiponectin, IL-6, bilirubin, and albumin with increasing age." (PMID 21170382, 2010). "The data further establish urinary collagen fragments as biomarkers for diabetes-induced renal damage that may serve as earlier and more specific biomarkers than the currently used urinary albumin." (PMID 20975990, 2010). "Urinary excretion of albumin should be monitored routinely in patients with diabetes mellitus." (PMID 20368924, 2009). "Determination of the urine albumin to creatinine ratio is an easy method for screening of microalbuminuria that is suggested for all diabetic patients, especially diabetic patients with hypertension and long-term diabetes." (PMID 20142916, 2008). "Another major finding of the present study was that the use of logistic regression model incorporating with glycated albumin, hs-CRP and other major independent risk factors commonly seen in type 2 diabetes was competent to screen and predict CAD in patients with diabetes (area under curve: 0.824)." (PMID 17178005, 2006). "In addition, screening with quantitative urinary albumin measurements is inadequately performed in patients with diabetes." (PMID 16539798, 2006). "Therefore, the sixteen variables, including Age, Diabetes, HB, TP, ALB, HDL-C, β-CTX, PTH, CSA, VB, FDR, 25-OH-D3, Number of fractured vertebrae, BMD, Exercise regularly after discharge, Anti-osteoporosis after discharge, were included in the multivariate Logistic regression model." (PMID 39911860, 2025). "Finally, results on microalbuminuria and the albumin/creatinine ratio are very much in line with large epidemiological studies (including in diabetes and hypertension), which consistently show that even mild increases in albumin excretion predict CVD events, heart failure, and mortality." (PMID 41597318, 2025). "Additionally, the data suggest that the association between urinary albumin excretion and vitamin D levels is independent of glycemic control in patients with diabetes." (PMID 41517402, 2025). "Adequate albumin not only serves as a nutritional marker but also synergistically regulates inflammatory responses through its antioxidant and anti-inflammatory properties, thereby demonstrating stronger compensatory capacity when facing diabetes-related metabolic stress." (PMID 41323966, 2025). "However, in patients with type 2 diabetes mellitus, decreased renal function suggests the risk of non-albuminuric diabetic kidney disease, even if the urinary albumin level is normal." (PMID 40060381, 2025). "To date, diabetes mellitus (DM), hypertension (HT), low preoperative hemoglobin and albumin levels have been considered among the known pharyngocutaneous fistula risk factors." (PMID 39915316, 2025).
diabetes (continued). "ROC curves were generated to evaluate the baseline risk model consisting of age,sex, smoking status, BMI, diabetes duration, hypertension, coronary heartdisease, cerebrovascular disease, MAP, fasting glucose level, HbA1c, and thefitting model of the baseline risk model and CRP/albumin ratio." (PMID 40622101, 2025). "Older age, higher plasma concentrations of CTGF and NT-proBNP, longer hemodialysis (HD) vintage, diabetes mellitus (DM), smoking, higher hs-CRP, and lower albumin were all significantly associated with increased mortality risk." (PMID 41373510, 2025). "In a diabetes-driven kidney disease model, Glp1r–/– mice with streptozotocin-induced diabetes exhibited spontaneous kidney dysfunction and accelerated kidney damage as evidenced by their higher albumin-to-creatinine ratios, increased fibronectin levels, and lower cystatin C levels in the urine." (PMID 41178710, 2025). "Third, this is a retrospective study, and we could not assess other possible confounders, such as lower albumin and the severity of risk factors, such as diabetes." (PMID 41158720, 2025). "Additionally, the increase of serum ALB could reduce the incidence of DR in individuals with diabetes (Model 3: OR = 0.95, 95% CI 0.92–0.97, p < 0.001)." (PMID 40612311, 2025). "Patients who developed CIN were significantly older and had a higher prevalence of diabetes mellitus (DM), worse baseline renal function, and lower levels of hemoglobin, albumin, HDL cholesterol, and lymphocytes (p < 0.001)." (PMID 41597302, 2025). "A similar finding has been previously reported in a pooled analysis of phase-2 and phase-3 RCTs only in patients with diabetes in whom the changes of urinary albumin-creatinine ratio after 24 weeks of dapagliflozin were of the same magnitude in patients whether receiving RAS inhibitors or not." (PMID 39834621, 2025). "These include age, diabetes mellitus, renal disease, history of catheter-associated infection, hypertension, dialysis duration, catheter site, catheter duration, number of catheterizations, catheter type, CD4+ cell, ALB, CRP, Hb, PCT, inadequate hand hygiene, and APACHE II scores." (PMID 38536779, 2024). "While we cannot investigate this hypothesis in our sample, a recent study following 46,675 patients with diabetes in Taiwan from 2003 to 2018 showed that low LDL-C increased the risk of death independent of the level of albumin." (PMID 39768591, 2024). "However, antibiotic prophylaxis (second-generation or third-generation cephalosporin), sex, preoperative albumin, diabetes mellitus, age, and ASA score were not significant risk factors." (PMID 38222754, 2024). "The tests that ought to be performed in every patient with diabetes include complete blood count with a smear (lymphopenia may be an indicator of malnutrition) and the concentration of total protein, albumin, folic acid, B12, ferritin, vitamin D3, calcium, uric acid, and lipid profile." (PMID 38612580, 2024). "Both drugs prevented foot process effacement and attenuated urinary albumin excretion, thereby contributing to a deeper understanding of the renal protective mechanisms associated with sodium glucose cotransporter 2 (SGLT2) and dipeptidyl peptidase-4 (DPP4) inhibitors in diabetes." (PMID 39201721, 2024). "Moreover, we note that several predictors identified in the scores were associated with factors influencing wound healing, such as age, albumin concentration, hemoglobin concentration, smoking, steroid use, diabetes, anticoagulation, immunosuppressant use, active neoplasia, and chronic conditions." (PMID 38418633, 2024). "Regarding the factors associated with sarcopenia risk, we found that higher body fat, lower socioeconomic status, lower education, insufficient physical activity, diabetes, smoking, malnutrition, and low serum albumin levels might increase the likelihood of sarcopenia." (PMID 39839289, 2024).